ID1 (inhibitor of DNA binding 1)
Diseases named in the same sentence as ID1 in open-access papers (continued):
Sharing a sentence is not in itself a finding about the gene and the disease.
tumor (continued). "ID1 has been reported to be associated with the undifferentiation of cancer cells, severe malignant grade of tumour, invasion of tumours and worse prognosis in several tumours." (PMID 19491902, 2009). "These provide evidence that clarifies the association between ID-1 overexpression and tumour angiogenesis in human primary cancer." (PMID 19002177, 2008). "Consistent with the results of previous studies, this study revealed that increased Id-1 expression was correlated with high grade and advanced stage tumours and that Id-1 expression was also significantly associated with EGFR expression." (PMID 19014499, 2008). "Increased Id-1 expression has been found to be associated with advanced stage tumours and poor prognosis." (PMID 19014499, 2008). "This study aims to recognise the specific types of high-risk HPV infections present in Syrian women and their association with tumour aggressiveness and Id-1 overexpression." (PMID 18648363, 2008). "By statistical analysis, we demonstrated that high-level cytoplasmic Id-1 expression was significantly (P=0.045) associated with T4 tumour." (PMID 18000500, 2007). "Loss of Id1 in the bone marrow (BM) severely impairs tumor angiogenesis resulting in significant inhibition of tumor growth." (PMID 18092003, 2007). "Since slower tumor growth in the Id1 mutant mice has been associated with decreased density and abnormal structure of the vasculature, we analyzed the vascular organization of the LLC tumors grown in the four different groups of mice." (PMID 18092003, 2007). "A high level of cytoplasmic Id-1 expression was significantly associated with T4 stage tumour (P=0.045)." (PMID 18000500, 2007). "In these studies, stronger ID1 expression was consistently associated with poorly differentiated tumours and a more aggressive behaviour." (PMID 16189525, 2005). "Increased ID1 expression was found in thicker tumours and was significantly associated with poor prognosis." (PMID 16189525, 2005). "Strong ID1 expression was significantly associated with increased tumour thickness, and significantly reduced survival." (PMID 16189525, 2005). "This is the first evidence that clarifies the association between Id-1 expression and tumour angiogenesis in human primary cancers." (PMID 15026801, 2004). "In the present study, Id-1 overexpression was found to be significantly associated with intratumoral microvessel proliferation, indicating that Id-1 has a significant role in tumour angiogenesis." (PMID 15026801, 2004). "ID1 is a downstream protein of this pathway and is, herein, associated with larger tumour size." (PMID 40826447, 2025). "Additionally, ID1 expression has been linked to increased tumor invasiveness and metastatic potential, highlighting its critical role in cancer progression." (PMID 40468582, 2025). "Similarly, the effector CD8+ T cells tumor infiltration was significantly increased among Id1-deficient animals as compared to Id1-expressing mice." (PMID 37841258, 2023). "ID1 deficiency in vitro significantly blunt the invasive tumor-formation related phenotypes." (PMID 35941362, 2022). "We also speculate that the level of ID1 will be inversely associated with HIF1α in clinical tumor samples." (PMID 34820369, 2021). "Moreover, co-culture assays demonstrated that Id1 deficiency in tumor cells increased the lethality of CD8+ T cells." (PMID 33126649, 2020). "This indicates that Id1 also plays a role in tumor-associated inflammation." (PMID 32410828, 2020). "Moreover, overexpression of ID-1 is associated with tumor angiogenesis and poor clinical outcome in OSCC." (PMID 30871117, 2019). "Furthermore, studies in PDAC cells have shown that activated Src can induce Id1 expression, thus suggesting that inhibition of Src signaling would interfere with the Id1-associated tumor growth as well." (PMID 31100813, 2019). "Results from this study may be applied to other processes associated with increased endothelial Id1 expression including tumor angiogenesis." (PMID 24516656, 2014).
tumor (continued). "Moreover, up-regulation of Id1 has been found in many types of human cancers and its expression levels are also associated with advanced tumor stage." (PMID 25010525, 2014). "Thus, cytoskeletal changes due to ID1 downregulation are associated with altered tumor cell invasion properties." (PMID 24137437, 2013). "Furthermore, ID1 overexpression has been associated with malignancy, poor clinical outcome or lung metastasis in different tumour types." (PMID 23555842, 2013). "Increased Id-1 levels are associated with poor prognosis in advanced stage tumours." (PMID 19014499, 2008). "This provides evidence that clarifies the association between Id-1 overexpression and tumour angiogenesis in human primary cancers and indicates Id-1 protein may be an important new target molecule for antiangiogenic drug design in cancer treatment." (PMID 15026801, 2004). "We provide the first evidence to clarify the association between Id-1 overexpression and tumour angiogenesis in human primary cancers and suggest that Id-1 protein may be an important new target molecule for antiangiogenic drugs in cancer treatment." (PMID 15026801, 2004). "The tumor suppressor activity of Smurf2 is related to the ability of Smurf2 to induce cell senescence when telomers are shortened, thus avoiding the accumulation of mutations by degrading Id1 (Inhibitor of DNA binding 1), which leads to the expression of p16 that is the ultimate senescence inducer." (PMID 34577077, 2021). "Also, overexpression of Hpa2 in H&N cancer cells resulted in a marked decrease in tumor growth, associating with a prominent reduction in tumor vascularity (blood and lymph vessels) likely due to reduced Id1 expression, a transcription factor highly implicated in VEGF-A and VEGF-C gene regulation." (PMID 33959505, 2021). "ID1 proteins, in association with ubiquitous E proteins, prevent CSCs from differentiating, thus determining the crucial “blocking event” that would confer to CSC1s persistent stemness, with self-renewal and pluripotency capacities, reiteratively feeding the tumor." (PMID 34295890, 2021). "Moreover, the expression of Id-1 in tumor cells has been associated with tumor malignancies." (PMID 26253141, 2015). "Thus, our findings support the hypothesis that ID1 interferes with centrosome homeostasis, most likely contributing to genomic instability and associated tumor aggressiveness." (PMID 20070914, 2010). "To further explore this, we analyzed the expression of ACVRL-1, the phosphorylation levels of Smad1/5/9, and the expression of ID-1 in tumor tissues." (PMID 41579221, 2026). "Further analysis revealed that ID1 expression was markedly elevated in tumors at stage I and stage II, and increased progressively with tumor grade from grade 1 to grade 3, suggesting a correlation with disease advancement." (PMID 40919143, 2025). "Functional assays, including wound healing and Transwell migration experiments, confirmed that ID1 downregulation correlates with decreased tumor cell motility." (PMID 40781861, 2025). "This indicates that the oncogenic effects of hypoxia are at least partially mediated by TRIM21 downregulation, and underscores TRIM21 as a key modulator of hypoxia-adaptive tumor behavior via post-translational control of ID1." (PMID 40919143, 2025). "The resulting differentially expressed genes were analysed via gene ontology (GO) enrichment analysis to identify pathways enriched in ID1 high expressing liver and lung tumours." (PMID 40116596, 2025). "We found that knockdown of ID1 significantly suppressed tumor growth, whereas silencing TRIM21 led to accelerated tumor progression." (PMID 40919143, 2025). "TRIM21 knockdown restored ID1 levels and promoted tumor cell function, whereas TRIM21 overexpression suppressed these malignant phenotypes and mitigated hypoxia-induced aggressiveness." (PMID 40919143, 2025).
tumor (continued). "With the relative ID1 expression patterns in the primary tumour, lung and liver metastases being highly reproducible between mice, these processes are not random but are likely to be dictated by the tumour microenvironment." (PMID 40116596, 2025). "In the same study, conditional activation of HrasᴧV12 in conjunction with constitutional activation of Id1 led to tumor formation, but doxycycline inactivation of the HrasᴧV12 promoter resulted in complete tumor regression within 40 days." (PMID 41303422, 2025). "For example, ID1 overexpression positively correlates with tumor growth, invasion and metastasis in patients with CC." (PMID 41020879, 2025). "Together, these findings suggest that hypoxia promotes ID1 stabilization predominantly through TRIM21 downregulation, thereby enhancing ID1-mediated signaling during tumor progression." (PMID 40919143, 2025). "To further verify that ID1 inhibits tumor angiogenesis and metastasis by upregulating TSP1, we used Western blotting to evaluate the expression of TSP-1." (PMID 40820992, 2025). "In contrast, our previous findings point to a tumor-suppressive function of BMP-9 in CRC by inducing ID1 whose expression is positively correlated with better survival in patients." (PMID 41378712, 2025). "Recently, various novel inhibitors of USP1 with satisfactory anti-tumor benefits have been developed to induce ID1 degradation, cellular differentiation, and apoptosis in leukemic cells." (PMID 41146039, 2025). "We simulated hypoxic conditions to assess their effects on ID1 expression and tumor cell behaviors, including proliferation, migration, and invasion." (PMID 40919143, 2025). "USP1 short hairpin RNA (shRNA) can rapidly degrade ID1, induce p21-mediated cell-cycle arrest, and initiate an osteogenic differentiation program in osteosarcoma, providing a target for tumor differentiation therapy." (PMID 41146039, 2025). "A large body of research has identified ID1 to be involved in cancer progression with roles in cellular transformation, proliferation, survival, colony formation, invasion, metastasis, tumour angiogenesis by ECs and chemoresistance (reviewed in Ref." (PMID 40116596, 2025). "Our results also implicate ID1 regulation of SERPINE1 (plasminogen activator inhibitor‐1 (PAI‐1)) which is reported to promote tumour vasculature by protecting ECs from apoptosis, and is associated with poor prognosis in cancer patients." (PMID 40116596, 2025). "For the downregulated genes, Id1, Tor4a, Fam83d, Chst12, Fhod1, Sapcd2, and Gas2l3 are known as proliferative and metastatic oncogenes contributing to tumor progression." (PMID 40231790, 2025). "Our data provides compelling evidence that hypoxia-mediated stabilization of ID1 exacerbates these tumor-promoting effects, while TRIM21 knockdown mitigates ID1-driven oncogenicity." (PMID 40919143, 2025). "Tumor‐derived TGF‐β switches DC differentiation to myeloid‐derived suppressor cells (MDSCs) though upregulating inhibitor of differentiation 1 (Id1), DNA binding inhibitor, promoting tumor progression and metastasis." (PMID 39083441, 2025). "Treatment with the BMP-receptor inhibitor LDN-212854, which inhibits both ALK1 and ALK2, suppressed HCC tumor growth by repressing ID1 and EpCAM in vivo in a xenograft mouse model of HCC." (PMID 41378712, 2025). "Research has demonstrated that ID1 is a necessary factor for neovascularization, including tumor angiogenesis, making the study of the relationship between the ID1 gene and tumors a new research hotspot." (PMID 40820992, 2025). "TRIM21 promotes SLC31A1 expression by enhancing ID1 ubiquitination, thereby inhibiting tumor growth and inducing cuproptosis via the TRIM21‐ID1‐TCF12‐SLC31A1 axis." (PMID 40652518, 2025). "In a Wnt-driven tumor, knockdown of Id1 and Id3 resulted in significant impairment of in vitro mammosphere generation and tumor initiation." (PMID 41303422, 2025).
tumor (continued). "This suggests that Id1 alone, even if constitutively expressed, cannot give rise to tumor development." (PMID 41303422, 2025). "Reducing ID1 expression improves colorectal cancer progression and improves tumor sensitivity to immunotherapy and chemotherapy." (PMID 40097979, 2025). "Inhibition of LIF was predicted to downregulate ID1-mediated functions including angiogenesis and the growth of a broad array of tumor cells." (PMID 38793603, 2024). "Several studies have shown that ID1 is highly expressed in most tumor tissues and is positively correlated with tumor invasion and metastasis." (PMID 39619441, 2024). "Overall, the presence of Id1 in LLC tumor cells impairs the antitumor activity of the combined treatment and restores an immunosuppressive tumor microenvironment." (PMID 38643157, 2024). "In view that trametinib treatment downregulates Id1 expression, we analyzed the effects of this treatment on Id1 expression and tumor growth in CMT167 and LLC KRAS-mutant LUAD syngeneic tumors." (PMID 38643157, 2024). "Nur77 suppresses ID1 expression to function as a tumor suppressor in a low TGFβ-signal environment, whereas, Nur77 promotes the growth of tumors by enhancing the effect of TGFβ on the induction of ID1 under situations of strong TGFβ signal." (PMID 38372868, 2024). "ID1 plays a negative regulatory role in normal conditions, inhibits cell differentiation, promotes tumor occurrence and angiogenesis." (PMID 39619441, 2024). "Analysis of patient tumor spheroids supported links between elevated autophagy, ID1 and SLC31A1 expression, and platinum sensitivity in clinical samples, thereby validating the relevance of these molecular connections in the highly aggressive HGSOC disease." (PMID 39123206, 2024). "Dinaciclib decreased LGR5 and ID1 expression levels and exhibited higher tumor growth suppressing effects than that of THZ531." (PMID 38182897, 2024). "The IPA analysis showed that NF-κB is one of the networks most strongly affected by jozimine A2, with downregulated expression of genes related to tumor progression, such as ID1 and VEGF." (PMID 38542061, 2024). "Using KRAS-mutant LUAD tumor mouse models we have identified that trametinib-mediated Id1 downregulation sensitizes KRAS-mutant LUAD tumors to anti-PD-1/PD-L1 blockade." (PMID 38643157, 2024). "In conclusion, we found that trametinib activates the proteasome to reduce Id1 levels in KRAS-mutant LUAD tumor cells." (PMID 38643157, 2024). "The protumoral phenotype conferred by Id1 expression in KRAS-mutant LUAD has been related to the induction of tumor angiogenesis, tumor-associated immunosuppression and metastasis." (PMID 38643157, 2024). "In the s.c. model, ML323 administration reduced ID1 expression in TAMs and manifested a marked tumor inhibition effect, as shown by the tumor volume and tumor weight compared with the vehicle group." (PMID 37996458, 2023). "Id1f/f-derived TAMs accelerated the tumor growth of MC38 cells, whereas depletion of Id1 attenuated the tumor-promoting role of TAMs." (PMID 37996458, 2023). "Similar to the enrichment of Orai3 in CSCs, ID1 exhibited elevated expression levels in tumor spheres in comparison to their corresponding monolayer adherent cells." (PMID 37759448, 2023). "ID1 enhances tumor progression, aggressiveness, and metastasis which are responsible for mortality in cancer patients." (PMID 37759448, 2023). "Id1 blockade in the tumor microenvironment (Id1-/- mice) significantly enhanced CD3+ T cell infiltration in tumor samples as compared to Id1+/+ mice." (PMID 37841258, 2023). "We found that the CM from RAW-Ctrl cells alleviated tumor cell growth and reduced the proportion of Ki67+ cells, while Id1 ectopic expression reversed these inhibitory effects." (PMID 37996458, 2023).
tumor (continued). "Of note, except for HOXA3, TWIST1, and ID1, the other seven genes are all proangiogenic genes that can be expressed and secreted by tumor cells, which implied the potential role of ELK4 in tumor angiogenesis in a paracrine manner in CRC." (PMID 37786278, 2023). "Depletion of Id1 in TAMs decreased the tumor-initiating cell frequency to nearly 1/3 (from 1/979 to 1/2,378)." (PMID 37996458, 2023). "To validate the involvement of CD8+ T cells in the tumor-promoting role of ID1 expressing TAMs, we depleted CD8+ T cells using systemic administration of an anti-CD8β antibody in a CT26 s.c. model." (PMID 37996458, 2023). "We investigated the synergistic impact of anti-PD-1 treatment combined with Id1 abrogation at the host tumor microenvironment." (PMID 37841258, 2023). "ID1 elicits its tumor-promoting effects by regulating various target genes involved in cancer development." (PMID 37759448, 2023). "High ID1 expression correlates with poor prognosis of cancer patients and increased tumor chemoresistance, angiogenesis, metastasis, and cancer stem cell properties." (PMID 37996458, 2023). "We further examined the expression of ID1 in HPCs in adjacent non‐tumor tissues in clinical patients and divided the patients into high‐expression and low‐expression groups." (PMID 37085918, 2023). "In contrast with the observations made regarding CD3+ T cell infiltration, CD8+ T cell infiltration was significantly higher in mice with complete Id1 depletion (tumor cells plus tumor microenvironment) (p > 0.0001; IDKO LLC_Sc/sh-ID1 p = 0.0497)." (PMID 37841258, 2023). "Mice injected with CM-derived from Id1f/f TAMs showed an enhanced bioluminescent signal, liver/body weight ratio, tumor diameter and number of hepatic lobes with metastatic tumor nodules, which were reversed when Id1 was ablated in TAMs." (PMID 37996458, 2023). "These vasculature genes included Efnb2, a member of the ephrin family and a pro-angiogenic factor whose overexpression predicts the poor prognosis of solid tumors, and Id1, a helix–loop–helix transcription factor that regulates tumor angiogenesis." (PMID 37047136, 2023). "89Zr uptake was significantly higher in mouse tumors when Id1 was inhibited at both the host microenvironment and tumor cells." (PMID 37841258, 2023). "The expression of the inhibitor of differentiation 1 (ID1) was found to be positively correlated with high tumor grade in CRC patience." (PMID 37664052, 2023). "When co-culturing with CD8+ T cells isolated from CRC patients’ peripheral blood mononuclear cells (PBMCs), ID1 depletion in TAMs isolated from CRC patients’ tumor tissues showed enhanced CD8+ T cell migration rate in comparison with the Ctrl group." (PMID 37996458, 2023). "We further confirmed that ML323 inhibited tumor progression partly through regulating ID1 expression in TAMs." (PMID 37996458, 2023). "Overall, our work identifies TAM-expressed ID1 as a central molecular node, dually controlling the cancer initiation capacity and inducing tumor immune evasion." (PMID 37996458, 2023). "Collectively, these data show that Id1 absence in the host microenvironment can induce tumor TIL infiltration." (PMID 37841258, 2023). "ID-1 has been shown to act through the p16ink4a/retinoblastoma (pRb) tumour-suppressor pathway, affecting telomerase activity." (PMID 36834513, 2023). "Among four ID family members (ID1-4), ID1 is the most extensively studied, and its role in cancer is generally considered as a tumor promoter." (PMID 37759448, 2023). "Transcriptome sequencing of TAMs isolated from MC38-derived tumor tissues in Id1f/f or Id1Lyz-KO mice was performed to explore how Id1 shaped the tumor-promoting phenotype of TAMs." (PMID 37996458, 2023). "Enzyme-linked immunosorbent assay (ELISA) validated that TAMs with Id1 depletion, isolated from CRC patient tumor tissues, MC38-derived tumor tissues or induced from BMDMs, showed increased CCL4 protein abundance." (PMID 37996458, 2023).